CTLA4 (cytotoxic T-lymphocyte associated protein 4)
Diseases named in the same sentence as CTLA4 in open-access papers (continued):
Sharing a sentence is not in itself a finding about the gene and the disease.
cancer (continued). "In general, cancer anti-adhesive immunotherapies have been unsuccessful in contrast with those targeting checkpoint inhibitors such as PD-1 and CTLA-4, which improve sustained T cell activation and show great improvement in some malignant tumors, such as metastatic melanoma." (PMID 30425987, 2018). "Several studies have investigated combined RT, PD-1/PD-L1, and CTLA-4 blockade while others have evaluated RT and immune checkpoint therapy with various combinations of chemotherapy, vaccine therapies, or targeted therapies across a spectrum of cancers." (PMID 29866197, 2018). "Targeting the regulatory immune checkpoints, inhibitors of programmed cell death 1 (PD1) and cytotoxic T-lymphocyte-associated protein 4 (CTLA4) signaling have demonstrated efficacy and have been approved as standard therapeutic options in several cancer types." (PMID 30170629, 2018). "The use of PD-1 and CTLA-4 blockade is rapidly expanding to a growing list of cancers." (PMID 29914571, 2018). "Antibodies targeting cytotoxic T-lymphocyte-associated protein 4 (CTLA-4) function act as potent cancer immunotherapeutics, but the tumors did not respond to CTLA blockade in antibiotic-treated or GF mice." (PMID 30294304, 2018). "CTLA-4 is the first immune check point targeted in the treatment of cancer." (PMID 29988281, 2018). "Therefore irAE and cancer immunity can be uncoupled genetically: whereas the human CTLA4 gene confers CITE responses to Ipilimumab in a dominant fashion, its role in conferring irAE is recessive." (PMID 29463898, 2018). "Notably, preclinical studies of anti-CTLA-4 and anti-PD-1 mAb combinations demonstrated promising results in a range of cancers." (PMID 28866656, 2018). "Then blockade of CTLA-4 may be a promising new approach to cancer therapy and constitutes a novel approach to induce host responses against tumors." (PMID 29707526, 2018). "Thus, our meta-analysis aims to illustrate the correlation between CTLA-4 expressions and overall survival (OS), as well as its prognostic role in cancer patients." (PMID 28211499, 2017). "In that context, the importance of therapeutically correcting immunosuppressive barriers in cancer patients has been recently highlighted by the impressive clinical results of immune checkpoint blockade using monoclonal antibodies against CTLA-4 and PD1/PDL144." (PMID 28928446, 2017). "Thus, our meta-analysis aimed to illustrate the prognostic role of CTLA-4 expression in several of cancers." (PMID 28211499, 2017). "Many PD-1 and CTLA-4 inhibitors, either as a single reagent, or in combination, have been permitted or tested in clinical trials by the United States Food and Drug Administration for the treatment of metastatic melanoma and other advanced cancers." (PMID 28703774, 2017). "In addition, rational combinations of TIM-3 mAbs with the PD-1 mAbs and/or CTLA4 mAbs have great potential to further improve the current immunotherapeutic approaches to cancer." (PMID 28300768, 2017). "The current success of targeted inhibition against cytotoxic T-lymphocyte-associated protein 4 (CTLA-4) and Programmed Death 1/Programmed Death Ligand 1 (PD-1/PD-L1, herein collectively referred to as PD) pathways is hailed as a cancer immunotherapy breakthrough." (PMID 28122590, 2017). "However, we didn’t observe any significant in the IHC subgroup (HR: 1.09, 95% CI: 0.66–1.78), as well as cancer subgroup (HR: 1.26, 95% CI: 0.97–2.03) and lymphocyte subgroup divided according to CTLA-4 sources (HR: 1.42, 95% CI: 0.64–3.14)." (PMID 28211499, 2017). "Immunotherapy, specifically, checkpoint inhibitor regimens such as nivolumab (anti-PD-1 monoclonal antibody) and ipilimumab (anti-CTLA-4 monoclonal antibody) target these receptors, thereby allowing the host immune system to mount a response against cancer cells." (PMID 29254501, 2017). "Knowledge of the effects of CTLA-4 could potentially be used to effectively guide appropriate prognosis and therapeutic strategies in cancer patients." (PMID 28211499, 2017).
cancer (continued). "Further studies on CTLA-4 cellular traffic and the differences in the expression of surface versus intracellular domains in the cancer environment could contribute to finding an accurate biomarker for therapy." (PMID 27866241, 2017). "Since then anti- CTLA-4 antibody tremelimumab, anti-PD-1 antibodies pembrolizumab and nivolumab and PD-L1 antibodies, atezolizumab and durvalumab, have shown beneficial effects in several cancers." (PMID 28228726, 2017). "Blockade of immune checkpoints, such as cytotoxic T-lymphocyte antigen-4 (CTLA-4) and programmed cell death-1 (PD-1)/ programmed cell death ligand-1 (PD-L1) signaling, have demonstrated broad anti-cancer activities with an acceptable side effect profile in different cancer types, including NSCLC." (PMID 28460468, 2017). "Breakthroughs have subsequently been made in clinical cancer immunotherapy by targeting checkpoints CTLA-4, and especially programmed cell death protein 1 (PD-1), which has resulted in United States Food and Drug Administration (FDA) approval for anti-CTLA-4 and anti-PD-1 therapies." (PMID 29211042, 2017). "Notably, ipilimumab, targeting CTLA-4 on T cells, allows T cell activation for immune responses in several cancers as well as inhibition of Treg function." (PMID 28572863, 2017). "The current clinical success, immune checkpoint inhibitors, is aimed to unleash antitumor immunity to eliminate cancer cells by specific blocking antibodies to cytotoxic T lymphocyte antigen-4 (CTLA-4) and programmed death-1 (PD-1), two inhibitory receptors in T cells to limit lymphocyte activation." (PMID 29238349, 2017). "The outcomes of studies analyzing the prognostic role of CTLA-4 in cancers are controversial." (PMID 28211499, 2017). "Blocking CTLA-4 for immunotherapy of cancer was later steered by James Allison who has played crucial roles in the renaissance of cancer immunology, whereas Chen’s earlier work laid the groundwork for the therapeutic potential of manipulating co-stimulatory molecules against cancer." (PMID 28122590, 2017). "Sixteen cancer patients were treated with PD-1/PDL-1 or CTLA-4 ICM at GKH between October 2013 and May 2016." (PMID 29237435, 2017). "Recently approved antibody therapies targeting inhibitory ICI proteins such as cytotoxic T lymphocyte-associated protein 4 (CTLA-4) and programmed cell death protein 1 (PD-1) and its ligand (PD-L1) have demonstrated valuable clinical benefit in the treatment of cancer." (PMID 28723950, 2017). "Therefore, the aim of our meta-analysis was to clarify the correlation between CTLA-4 expression and OS in different cancer cases." (PMID 28211499, 2017). "We also analyzed the percentage of lymphocyte subsets (CD4+, CD8+ and CD19+) expressing surface and/of intracellular CTLA-4 in cancer patients and healthy volunteers, aiming to figure out the correlation between lymphocytes CTLA4 locations and their susceptibility to cancers." (PMID 28211499, 2017). "Interestingly, the pooled HR for OS was 1.47 (95% CI: 1.14–1.89) in SNP subgroup, which suggested that CTLA-4 +49AA genotype was an independent adverse indicator for cancer prognosis." (PMID 28211499, 2017). "Only a few subsets of cancer patients benefit from anti-PD-1 and anti-CTLA-4 therapy and these targeted medicines may induce unavoidable side effects." (PMID 29225597, 2017). "In this review, we will go through the role of promising monoclonal antibodies in cancer immunotherapy with immunomodulatory function, especially blocking of the inhibitory immune checkpoints CTLA-4 and PD-1, in combination with different immunotherapeutic strategies such as vaccines." (PMID 28970830, 2017). "Instead of eliciting a target-antigen-directed immune response in the context of a cancer vaccine, the pharmacologic interference with inhibitory immune checkpoints such as CTLA-4 or the PD-1/PD-L1 axis restored cytotoxicity of preexisting, exhausted cancer-specific T cells." (PMID 29312332, 2017).
cancer (continued). "Elevated levels of CD4+ T cells co-expressing CTLA-4 and PD-1 also support the dual blockade of these immunosuppressive pathways, which could be a more effective method for treating different cancers including breast." (PMID 28388539, 2017). "Similarly cytotoxic T-lymphocyte-associated protein-4 (CTLA-4) is expressed by activated T cells, which acts as an immune checkpoint and downregulates immune responses against cancer cells." (PMID 29254501, 2017). "Clinical success of antibodies to CTLA-4 and PD-1 has rekindled the hope for cancer immunotherapy." (PMID 29029399, 2017). "In addition, at present, immune checkpoint blockades, such as anti-PD-1/PD-L1 or anti-CTLA-4 antibodies, are considered to be the most promising drugs for treatment of advanced cancer patients." (PMID 27757561, 2017). "Ipilimumab and tremelimumab are monoclonal antibodies targeting CTLA-4 for cancer therapy." (PMID 28703774, 2017). "Indeed, treatment based on the blockade of immune checkpoints such as PD-1 or CTLA-4, have demonstrated major clinical benefit for cancer patients." (PMID 28594868, 2017). "The effect of CTLA-4 +49AA genotype on the development, progression and prognosis of cancers may due to the interference with the transcriptional activity of CTLA-4 mRNA level." (PMID 28211499, 2017). "Importantly, the blockade of CTLA-4 and PD-1/PD-L1 is being extended to the treatment of other cancers and combination therapies, which utilize checkpoint inhibitors with other immunotherapy approaches, are being explored [reviewed in Ref." (PMID 29033936, 2017). "Indeed, it has been reported that cancer patients treated with anti-CTLA-4 (Ipilimumab) or anti-PD-1 (Nivolumab or Pembrolizumab) blocking antibodies showed an increase of the antitumor T-cell response and a higher rate of disease free survival." (PMID 28594868, 2017). "Other mechanisms that could also explain the antitumor efficacy of the combination of cancer vaccine with blockade of checkpoint inhibitors, especially anti-CTLA-4, include the decreased frequency of myeloid-derived suppressor cells." (PMID 27827885, 2016). "Furthermore, CTLA-4 protein expression in cancer appears to be important for tumors to evade host immune surveillance." (PMID 27050369, 2016). "However, our results on CTLA-4 blockade provided potential reasons for the failure of immunotherapy for cancer and suggested the need for future studies on immunomodulators against cancer." (PMID 27105511, 2016). "To date, immune checkpoint blockade therapies are performed against selected cancer entities using antibodies against the CTL-associated antigen-4 (CTLA-4), against the PD1 receptor, and against its ligand PD-L1, with success rates varying in the different cancer entities." (PMID 27579535, 2016). "Similar to expression of CTLA4, this PD-L1 protein is also expressed by various types of cancer cells which may be a mechanism for how the cancer escapes immunity." (PMID 28116316, 2016). "Currently inhibitors of the immune checkpoints CTLA-4 (cytotoxic T-lymphocyte-associated protein 4) and CD274 (Programmed death-ligand 1, PD-L1 or B7H1) have been approved for the treatment of several cancer types, further underlining the importance of this pathway." (PMID 27683114, 2016). "The impact of this scientific achievement is reflected by the fact that James P. Allison has been recently awarded the 2015 Lasker-DeBakey Clinical Medical Research Award for the discovery and development of an anti-CTLA-4 mAb that releases the brakes of the immune system to combat cancer." (PMID 27151159, 2016). "Third, the correlation of CTLA4 and PD-1 expression with CD8 T-cell abundance suggests that a subset of patients from most cancer types may benefit from combined use of anti-CTLA4 and anti-PD-1 agents." (PMID 27549193, 2016). "The prognostic role of CTLA4 has been explored in several types of cancers." (PMID 26918337, 2016).
cancer (continued). "This is illustrated by the explosive preclinical and clinical progress recently made with immune checkpoint blockade, wherein therapeutic antibodies are used to block cancer cells from engaging cytotoxic T-Lymphocyte antigen 4 (CTLA-4) or programmed death 1 (PD-1) receptors on T lymphocytes." (PMID 27240403, 2016). "It is a monoclonal antibody targeting CTLA4 on T cells; thereby it inhibits the suppressive effects of CTLA4 on T cells and allows activation of T cells for immune responses against specific cancers." (PMID 28116316, 2016). "The recent clinical success of nivolumab, an anti-programmed death-1 (PD-1) mAb, and ipilimumab, an anti-cytotoxic T lymphocyte-associated protein-4 (CTLA-4) mAb, may bring about a paradigm shift in the treatment of patients with advanced cancer." (PMID 25686210, 2015). "Notably, the analysis highlighted different T-cell activation pathways in different cancer types, particularly the CTLA4, CD28 and iCOS-iCOSL signalling pathways in T cells, which are the key pathways in anti-CTLA-4 immunotherapy treatments." (PMID 26634437, 2015). "Furthermore, advances in the field of cancer immunotherapy provide indication on the impact of CTLA-4 blockade, including on a preexisting immune response." (PMID 26322044, 2015). "Tregs constitutively express CTLA-4 and the benefit seen with CTLA-4 antibody therapy in cancer may in part be attributed to Treg depletion." (PMID 26834735, 2015). "Novel strategies in the field of immune-oncology have also led to the development of inhibitors of cytotoxic T lymphocyte antigen-4 (CTLA-4) and programmed death-1 receptor (PD-1), which are important pathways in allowing cancer cells to escape detection by the immune system." (PMID 26371045, 2015). "CTLA-4 blockade enhanced antitumor efficacy when combined with other immunomodulating agents, including Granulocyte Macrophage-Colony Stimulating Factor (GM-CSF) and GM-CSF-secreting cancer vaccines, e.g. GVAX immunotherapy." (PMID 26196012, 2014). "In summary, this case-control study along with a meta-analysis, failed to confirm the association between CTLA-4 -1722T/C polymorphism and cancer risk, even across different ethnic subgroups and different systems." (PMID 24710335, 2014). "Given that minor changes in the surface expression of the co-receptor are expected to have significant effects on responses to autoantigen and in cancer immunotherapy, it is important to understand the mechanisms that determine the expression of CTLA-4 on T-cells." (PMID 25538704, 2014). "In addition, blocking immune system regulatory checkpoints with antibodies (e.g. anti-CTLA-4 or anti-PD-1) is providing additional avenues for cancer immunotherapy." (PMID 24736661, 2014). "To further investigate CTLA4-FasL mode-of-action in cancer cell line, we studied if CTLA4-FasL cytotoxic effect can be abrogated by the pan-caspase inhibitor (Z-VAD), caspase 8 inhibitor (Z-IETD-FMK) and caspase 9 inhibitor (Z-LEHD-FMK) on malignant cell lines positive for Fas only." (PMID 25227919, 2014). "For the purpose of cancer immunotherapy, monoclonal antibodies have been generated to potentiate the ongoing antitumor immune response of the patient, through “immune checkpoint blockade” of CTLA-4, PD-1, or PD-1 ligand (PD-L1)." (PMID 24860567, 2014). "In addition to CTLA-4, a number of immune-checkpoints are also being targeted in cancer immunotherapy." (PMID 24904570, 2014). "Of late, Geng and colleagues reported a meta-analysis with a negative result on the association between CTLA-4 -1722T/C polymorphism and cancer risk." (PMID 24710335, 2014). "Recent approval of Sipuluecel-T, which is cancer vaccine with an activated antigen presenting cells and lymphocyte mixture for hormone refractory prostate cancer and anti-CTLA4 mAb (Ipilimimab) for melanoma implicate a new era of the immunotherapy in the anti-cancer strategy." (PMID 22776426, 2012).
cancer (continued). "Indeed, several phase I/II trials using humanized monoclonal antibodies (mAbs) to block CTLA-4 signaling have shown promising results in different human cancers." (PMID 21127709, 2010). "It is more likely that the same threshold of CTLA4 blockade may lead to activation of lymphocytes reactive to self-tissues and cancer." (PMID 19457253, 2009). "The significant negative correlation of NUP62 with CTLA-4 may imply that the low expression of NUP62 in these two cancers is associated with an attenuated immunosuppressive state." (PMID 40098960, 2025). "A single-gene CTLA4 score may be combined with other gene expression assays and used for de-escalation of adjuvant and neoadjuvant chemotherapy, thereby preventing side effects and improving the quality of life for cancer survivors." (PMID 40523912, 2025). "In the context of cancer therapy, where immune checkpoint inhibitors, such as ipilimumab, nivolumab, and pembrolizumab, have proven effective, we observed that Wnt pathway activity significantly correlated with CTLA-4 expression, a key marker of response to these therapies." (PMID 40002717, 2025). "Likewise, the efficacy of various cancer immunotherapies approved by the FDA, such as anti-CTLA-4 and anti-PD-1, could be linked to their impact on Tregs as well as enhancing Teff cell destruction." (PMID 40224950, 2025). "Indeed, the advent of ICIs targeting CTLA-4, PD-1, and PD-L1 transformed cancer therapy." (PMID 40536609, 2025). "Indeed, parallels can be drawn with immunotherapeutic approaches currently being investigated in HPV-driven human cancers, such as checkpoint inhibition (PD-1/PD-L1, CTLA-4 blockade), therapeutic vaccines, and nanoparticle-mediated delivery of viral antigen targets." (PMID 41157593, 2025). "However, as the cancer progresses, CTLA-4 expression may increase, contributing to immune evasion by the cancer cells." (PMID 39941799, 2025). "MARCH1 and CD83, in addition to PD-1 and CTLA-4, are promising immune regulators that can be explored to activate host immune responses, including activation of T-helper cells and production of IFN-I that appear to be associated with successful immunotherapy for cancers." (PMID 39847577, 2025). "Anti-CTLA4 and anti-PD-L1/PD-1 therapeutic antibodies have revolutionized the field of clinical oncology, enabling physicians to advance therapy beyond traditional chemotherapy and RT, thereby increasing curability and prolonging the survival of patients with previously incurable cancers." (PMID 41614858, 2025). "The similar patterns of treatment response and safety profiles observed in anti-CTLA-4 antibody therapy for dogs with spontaneous cancers support the hypothesis that canine cancers are relevant models for human cancers, particularly in the context of ICI therapies." (PMID 40463388, 2025). "The use of immune checkpoint inhibitors like anti-PD-1 and anti-CTLA-4 has already proven successful in boosting T cell responses, and combining these therapies with engineered T cells may become a standard strategy to enhance cancer immunotherapy." (PMID 41186710, 2025). "Furthermore, combined ICI therapy poses a breakthrough in the treatment of some types of cancer, such as non-small-cell lung cancer and metastatic melanoma, in which the concomitant administration of ipilimumab (anti-CTLA-4) and nivolumab (anti-PD-1) increases the response rate and survival." (PMID 40149687, 2025). "Furthermore, the identification of immune checkpoint proteins like CTLA-4 and PD-1 unveiled critical pathways by which cancer cells evade immune surveillance, and the development of immune checkpoint inhibitors revolutionized cancer treatment paradigms." (PMID 39982231, 2025). "There have been several PD-1/PD-L1 and CTLA-4 monoclonal antibodies approved for cancer treatment; thus, designing BsAbs using biochemical engineering to target different immune checkpoints seems to provide a promising effective treatment strategy in cancer therapy." (PMID 40565299, 2025).